FLG (filaggrin)
Diseases named in the same sentence as FLG in open-access papers (continued):
Sharing a sentence is not in itself a finding about the gene and the disease.
atopic dermatitis (continued). "Filaggrin, which is encoded by the filaggrin gene (FLG), is an important component of the skin's barrier to the external environment, and genetic defects in FLG strongly associate with atopic dermatitis (AD)." (PMID 27913303, 2017). "Prevalent mutations in the gene encoding filaggrin (FLG), a key skin-barrier protein, represent the strongest and most consistent known genetic risk factor for atopic eczema." (PMID 28732519, 2017). "For some time now, and not least in a systematic review and meta-analysis, the strong relation between Filaggrin gene (FLG gene) mutations and atopic eczema has been documented." (PMID 30402617, 2017). "Mutations in the gene encoding for filaggrin (FLG) are major predisposing factors for atopic dermatitis (AD)." (PMID 28377574, 2017). "In line with that observation, a recent study of atopic dermatitis reported that there was a high frequency of filaggrin (FLG) null alleles detected in children of European origin with both atopic dermatitis and asthma phenotype." (PMID 28359274, 2017). "A loss of FLG function is associated with several skin diseases such as ichthyosis vulgaris and atopic dermatitis." (PMID 26966508, 2016). "Mutations in the gene encoding filaggrin (FLG), an epidermal structural protein, are the strongest risk factor identified for the development of atopic dermatitis (AD)." (PMID 26934939, 2016). "Mutations in the gene encoding filaggrin (FLG), an epidermal structural protein, are associated with different phenotypes: atopic dermatitis (AD), ichthyosis vulgaris (IV), or clinically normal skin." (PMID 26934939, 2016). "Loss-of-function (LOF) mutations in the filaggrin gene (FLG) are a well-replicated risk factor for atopic dermatitis (AD) and are known to cause an epidermal barrier defect." (PMID 26071937, 2015). "The discovery of filaggrin gene mutations as a predisposing factor for atopic dermatitis and subsequent asthma and sensitization in the context of eczema has redefined our view on the allergic march." (PMID 26557262, 2015). "Mutations in the filaggrin (FLG) gene are associated with atopic dermatitis and ichthyosis vulgaris." (PMID 25739514, 2015). "Mutations in the gene encoding filaggrin (FLG) are associated with immune sensitization in allergic dermatitis and asthma and these mutations cause an impairment of the skin barrier function." (PMID 26573531, 2015). "Loss-of-function mutations in the filaggrin gene situated on chromosome 1q21 were first associated with the skin disease ichthyosis vulgaris and more recently with atopic dermatitis." (PMID 26557257, 2015). "The advent of filaggrin gene mutations holds promise that progression of the allergic march from atopic dermatitis to asthma can be halted by treating the skin barrier defects in infants and very young children." (PMID 26557262, 2015). "Filaggrin proteins are essential for the formation of a cornified envelope, and a loss-of-function mutation has been described in humans with atopic dermatitis." (PMID 25098772, 2014). "A recent and interesting genetic discovery is the documented strong association between atopic dermatitis and mutations in the filaggrin gene, positioned on chromosome 1." (PMID 25006501, 2014). "We confirmed that the filaggrin gene mutation c.3321delA is associated with atopic dermatitis in our previous genome wide association study of the Chinese Han population." (PMID 24858702, 2014). "Atopic dermatitis and icthyosis vulgaris are inflammatory skin conditions caused by inactivating germ-line mutations of the FLG gene in some cases." (PMID 24988487, 2014). "The theory of skin barrier defects is more recent and has its origin in the observation that individuals with mutations in the filaggrin gene are at increased risk of developing atopic dermatitis." (PMID 25006501, 2014). "The filaggrin gene mutation c.3321delA was sequenced in 1,080 atopic dermatitis patients and 908 controls from the Chinese population." (PMID 24858702, 2014).
atopic dermatitis (continued). "FLG loss-of-function mutations are predisposing factors for the very common human skin conditions icthyosis vulgaris and atopic dermatitis (eczema)." (PMID 25449884, 2014). "The number of babies with a loss-of-function mutation in the skin barrier gene filaggrin, the strongest known genetic predictor of atopic dermatitis, was also similar between the 2 groups." (PMID 25282563, 2014). "The aim of this study was to correlate the flaky tail mouse phenotype with human IV and AD, in order to dissect early molecular events leading to atopic dermatitis in mice and men, suffering from filaggrin deficiency." (PMID 23844115, 2013). "Nonetheless, previous studies have found an inverse association between type 1 diabetes and atopic dermatitis also suggestive of a protective role of loss-of-function mutations in FLG in diabetes." (PMID 24367652, 2013). "Alopecia areata in humans has been correlated to filaggrin mutations and development of atopic dermatitis." (PMID 23671420, 2013). "Atopic dermatitis (AD) is a major inflammatory condition of the skin caused by inherited skin barrier deficiency, with mutations in the filaggrin gene predisposing to development of AD." (PMID 24084074, 2013). "The results of filaggrin gene mutations are striking as several studies have demonstrated that the severity of atopic dermatitis correlates with the number of filaggrin gene defects." (PMID 22619686, 2012). "In children, filaggrin mutations seem to define a specific endotype of atopic dermatitis primarily characterized by predilection to exposed areas of the body, in particular hands and cheeks, and an up-regulation in both acute and chronic morphological markers." (PMID 23166590, 2012). "Analysis of associations between combined common filaggrin gene mutations and atopic dermatitis associated phenotype." (PMID 23152869, 2012). "Filaggrin gene mutations were linked directly to atopic dermatitis, allergic rhinitis, and the development of asthma in children." (PMID 22619686, 2012). "Filaggrin-deficient atopic dermatitis patients have decreased filaggrin-derived natural moisturization factors." (PMID 22619686, 2012). "Mutations of the filaggrin gene have been associated with ichthyosis vulgaris and persistent atopic dermatitis." (PMID 22619686, 2012). "This critical function of acidification and hydration of the skin has been linked to filaggrin gene defects in atopic dermatitis." (PMID 22619686, 2012). "Barrier function disorder due to filaggrin (FLG) mutations is critical in the pathogenesis of atopic dermatitis." (PMID 22523502, 2012). "Genetics are important in the aetiology of atopic eczema: in particular, recent genetic epidemiological studies found a strong association between filaggrin gene defects (present in 1 in 10 Europeans and North Americans), and atopic eczema." (PMID 22808063, 2012). "We aimed to characterize the clinical presentation and course of atopic dermatitis associated with filaggrin mutations within the first 7 years of life." (PMID 23166590, 2012). "Association analysis of filaggrin mutations with atopic dermatitis in both family and case-control studies." (PMID 23152869, 2012). "Filaggrin null mutations result in impaired skin barrier functions, increase the risk of early onset atopic dermatitis and lead to a more severe and chronic disease." (PMID 23166590, 2012). "The recent identification of mutations in the gene encoding the key epidermal protein filaggrin (FLG) as a remarkably strong and widely replicated risk factor for atopic dermatitis (AD) has led to a new focus on skin barrier deficiency in patients with AD." (PMID 22322004, 2012). "Meta-analysis of filaggrin polymorphism data has identified a genetic alteration in filaggrin as a significant risk for development of atopic dermatitis." (PMID 22619686, 2012).
atopic dermatitis (continued). "It is also interesting that mutations in the filaggrin gene not only cause atopic dermatitis, but also lead to a significantly increased risk for other allergic diseases and asthma in the context of eczema." (PMID 22410284, 2011). "Loss-of-function mutations within the filaggrin gene are associated with atopic dermatitis and other atopic diseases; therefore, filaggrin is a candidate gene in the etiology of peanut allergy." (PMID 21377035, 2011). "The association of filaggrin mutations with peanut allergy remains significant (P = .0008) after controlling for coexistent atopic dermatitis." (PMID 21377035, 2011). "Filaggrin mutations have been identified constantly in atopic dermatitis and this provoked increasing interest in studies trying to identify the epithelial barrier dysfunction in allergic diseases." (PMID 22410284, 2011). "Loss-of-function mutations in the filaggrin gene are linked to atopic dermatitis and other related diseases including peanut allergy." (PMID 22410284, 2011). "In this study, we investigated the levels of several breakdown products of filaggrin in the SC in healthy controls (CTRL) and patients with atopic dermatitis (AD) in relation to FLG null allele status." (PMID 21261659, 2011). "Patients with atopic dermatitis have an increased frequency of the most common filaggrin null mutations (R501X and 2282del4) compared to those with wasp allergy and healthy subjects." (PMID 22410284, 2011). "An important breakthrough in understanding occurred with the identification of null mutations in the gene encoding filaggrin (FLG) on chromosome 1q21 as a major risk factor for atopic eczema." (PMID 20109745, 2010). "Common loss-of-function mutations within the FLG gene causing ichthyosis vulgaris, filaggrin units represent major risk factors for atopic dermatitis (AD) and secondary allergic diseases." (PMID 19384417, 2009). "Recent genetic studies have shown that mutations within the gene encoding the SFTP filaggrin cause ichthyosis vulgaris and are major predisposing factors for atopic dermatitis." (PMID 19384417, 2009). "HFE rs1800562 causing hereditary hemochromatosis presented the highest frequency (7.54%), followed by BTD rs13078881 for biotinidase deficiency (7.08%), FLG rs61816761 for ichthyosis vulgaris and atopic dermatitis (3.38%), and FANCM rs147021911 for Fanconi anemia (3.08%)." (PMID 40763936, 2026). "Indeed, a loss-of-function mutation or deficiency in the FLG gene has been well-characterized as the strongest known genetic risk factor for skin barrier dysfunction in atopic dermatitis." (PMID 40078968, 2025). "Prevalent FLG gene mutations are R501*, 2282del4, R2447*, and S3247*; these may be associated with atopic dermatitis in 37–50% of cases." (PMID 40282340, 2025). "In atopic dermatitis, rare-variant analyses have highlighted FLG as a potential cross-disease gene." (PMID 41465136, 2025). "Skin barrier dysfunction underlies the initiation and perpetuation of inflammatory dermatoses such as atopic dermatitis, psoriasis, and ichthyoses, where disruptions in lipid composition, filaggrin deficiency, and impaired tight junction integrity contribute to disease chronicity." (PMID 40734872, 2025). "Mutations of filaggrin (FLG) are associated with atopic dermatitis." (PMID 41002986, 2025). "Mutations that induce functional changes in the filaggrin protein—a protein that binds to keratin fibers in the epithelial cells of the stratum corneum and helps maintain skin barrier integrity—have been associated with an increased risk of atopic dermatitis." (PMID 40095628, 2025). "Candidate gene association studies indicate that mutations in the filaggrin (FLG) gene are the most significant known risk factors for atopic dermatitis (AD), and genes in the type 2 T helper lymphocyte (Th2) signaling pathways are the second most replicated genetic risk factors for AD." (PMID 39201625, 2024).
atopic dermatitis (continued). "The main causes of atopic dermatitis are thought to be skin barrier dysfunction due to decreased filaggrin expression, as well as a dysregulated immune response and IgE autoreactivity, while otitis media and herpes simplex are both diseases with infectious genesis, either bacterial or viral." (PMID 37589869, 2024). "In addition, previous study on atopic dermatitis demonstrated that OVOL1 regulates Filaggrin expression and Ovol1-deficient keratinocytes showed reduced expression of Filaggrin in the suprabasal compartment of epidermis." (PMID 38907248, 2024). "In addition to the reduced FLG expression due to FLG gene mutations, the Th2 cytokine milieu in patients with atopic dermatitis can itself contribute to acquired FLG deficiency." (PMID 39676858, 2024). "Carriers ofFLG gene mutations associated with loss of filaggrin functionhave an increased risk of developing atopic dermatitis and bronchial asthma in the contextof atopic dermatitis, while at the same time the risk of asthmawithout atopic dermatitis is reduced." (PMID 36923482, 2023). "Additionally, keratoconus patients with atopic dermatitis were found to have a lower-than-expected frequency of filaggrin (FLG) mutations, despite FLG mutations being a strong genetic risk factor for atopic dermatitis." (PMID 37374145, 2023). "For example, the identification of loss-of-function nonsynonymous coding genetic variants within the filaggrin (FLG) gene in ~10% of atopic dermatitis patients led to further studies revealing the role of FLG in the development of a healthy epidermis and atopic dermatitis pathogenesis." (PMID 36585519, 2023). "The main genetic risk factor in atopic dermatitis is FLG loss-of-function mutations." (PMID 36660532, 2023). "The FLG gene is an important epidermal protein that promotes skin barrier function and its mutations remain the most easily replicated and important risk factor for atopic dermatitis." (PMID 35510248, 2022). "A controversy over the association between allergic dermatitis and FLG null mutations exists." (PMID 35628125, 2022). "FLG loss-of-function mutations reduce the skin barrier function and these mutations have been identified as a risk factor for different allergic diseases such as atopic eczema." (PMID 34836034, 2021). "Intriguingly, mature keratinocytes achieve resistance against pore-induced injury by secreting sphingomyelinase via lamellar bodies to limit the availability of α-toxin receptor, a strategy disrupted in atopic dermatitis patients with mutations in filaggrin (FLG)." (PMID 33849525, 2021). "Intriguingly, a decreased expression of FLG has been recorded in the autosomal semi-dominant disease ichthyosis vulgaris (IV) and in atopic dermatitis (AD), where the presence of loss-of-function mutations in FLG also predisposes to IV and AD as well as additional allergic diseases such as asthma." (PMID 34680271, 2021). "Moreover, both diseases are associated with a major genetic risk factor, i.e., Filaggrin (FLG) loss-of-function mutations in atopic dermatitis and the HLA-Cw0602 allele in psoriasis vulgaris." (PMID 34298981, 2021). "In atopic dermatitis (AD), skin barrier function is impaired by several mechanisms, including filaggrin deficiency, injury (itch), and type 2 cytokines (e.g., IL-4 and IL-13) altering TJ protein expression, thereby precipitating allergic sensitization and inflammation." (PMID 32595651, 2020). "Filaggrin plays a critical role in the structural and mechanical integrity of stratum corneum as shown in loss-of-function mutations of human filaggrin gene in defective barrier function of atopic dermatitis." (PMID 32806619, 2020). "Similarly, autosomal dominant ichthyosis vulgaris (IV; common dry skin) requires factors other than filaggrin (Flg)-null variants to manifest as atopic dermatitis (AD; eczema) or other allergic conditions." (PMID 32823937, 2020).
atopic dermatitis (continued). "Although atopic dermatitis is a representative skin disorder with barrier abnormalities, particularly related to filaggrin, the relevant miRNAs have been implicated in cell differentiation, proliferation, and anti-apoptosis in connection with barrier abnormalities." (PMID 32806619, 2020). "The mild barrier defects in the skin of newborn ninein-knockout mice are reminiscent of defects found in skin disorders such as atopic dermatitis, where reduced protein levels of filaggrin and defects in the cornified layer have been implicated in pathogenesis." (PMID 30923192, 2019). "Similarly, it is also reported that AhR improves the function of the skin barrier by activating the expression of filaggrin, and that there is a significant increase in dry skin phenotypes in atopic dermatitis patients with AhR polymorphism." (PMID 31216667, 2019). "Appropriate scientific papers were selected on the PubMed using the following headings and keywords, and their combinations: filaggrin, profilaggrin, filaggrin mutations, atopic dermatitis, eczema, epidermal dysfunction, allergic rhinitis, food allergies and asthma." (PMID 31223255, 2019). "Interestingly, the gene for PDZK1, a known protein that interacts with MAP17, is localized within the atopic dermatitis-linked region on human chromosome 1q21, such as the filaggrin gene." (PMID 29650022, 2018). "Moreover, patients with atopic dermatitis and filaggrin loss-of-function mutations are prone to a dose-dependent increase in sensitization with increasing peanut dust levels." (PMID 30347643, 2018). "Filaggrin (FLG) mutation is a well-confirmed genetic aberration in atopic dermatitis (AD)." (PMID 28703805, 2017). "Moreover, filaggrin mutations have been associated with development of allergic sensitisation, hay fever, and asthma, but only in subjects with atopic dermatitis." (PMID 26557257, 2015). "This hypothesis should be tested in future studies because it may be relevant for the effects of protein-truncating human FLG mutations in ichthyosis vulgaris and atopic dermatitis." (PMID 25739514, 2015). "The aetiology of atopic dermatitis is unknown, but the recent discovery of filaggrin mutations holds promise that the progression of atopic dermatitis to asthma in later childhood may be halted." (PMID 25006501, 2014). "Filaggrin gene defects are strongly associated with atopic eczema." (PMID 25033453, 2014). "Our study indicates that the filaggrin gene mutation c.3321delA is associated with clinical phenotypes of atopic dermatitis in the Chinese Han population, which might help us gain a better understanding on the pathogenesis of atopic dermatitis." (PMID 24858702, 2014). "The filaggrin gene is the strongest known genetic risk factor for atopic dermatitis." (PMID 25006501, 2014). "Whether these potentially beneficial effects of coal tar will be limited to atopic dermatitis associated with filaggrin mutations or whether AHR activation may provide general benefit to this inflammatory skin disease is currently unknown." (PMID 24904982, 2014). "In addition, loss-of-function mutations in the filaggrin gene have been identified as a major predisposing factor for atopic dermatitis." (PMID 24904982, 2014). "Filaggrin deficiency is the major predisposing factor for atopic dermatitis." (PMID 23615774, 2013). "Indirectly, our results suggest that very early therapeutic intervention in atopic dermatitis associated with filaggrin deficiency may be essential for disease prevention." (PMID 23844115, 2013). "Skin barrier abnormalities in atopic dermatitis may result from mutations in the gene encoding for filaggrin, which plays an important role in the formation of cornified cytosol." (PMID 22956938, 2012).